WNT1 (Wnt family member 1)
Diseases named in the same sentence as WNT1 in open-access papers (continued):
Sharing a sentence is not in itself a finding about the gene and the disease.
tumor (continued). "The anti-tumor efficacy of the treatment was further verified by the suppression of mouse mammary tumor virus (MMTV)-Wnt1 transgenic tumor via Wnt signaling pathway blocking." (PMID 33212974, 2020). "Another way in which the miR-34 family contributes to tumour suppressive function is that miR-34a, miR-34b*, and miR-34c-5p inhibit the Wnt pathway by repression of Wnt ligand co-receptors (WNT1/3; LRP6), with HMG-box transcription factor (LEF1) and β-catenin." (PMID 31658284, 2019). "Implantation of Wnt1 overexpressing vs. control Fula cells in the lungs of syngeneic mice resulted in faster tumor growth and decreased CD8+ T cell infiltration." (PMID 30926812, 2019). "To further substantiate the role of cDCs we proceeded to intratumoral cDC purification and analyses, using RAG mice as hosts, as they had shown minor differences in tumor growth upon inoculation of Wnt1-LLC or Empty-LLC cells." (PMID 30926812, 2019). "When measuring the relative tumor fractions of these populations, it was observed that Wnt1-LateEx tumors contained a higher fraction of Krt5-positive cells (P=0.02) and Krt8/18-positive cells (P=0.001) than Wnt1-EarlyEx tumors." (PMID 31213486, 2019). "It is, therefore, probable that Wnt1 mediates cellular interactions within the tumor microenvironment." (PMID 31799196, 2019). "Tumor tissue lysates of the CT26Flag−CAGE1 cells showed higher expression of Wnt1, β-catenin, pGSK3βSer9, and cyclin D1 than the tumor tissue lysates of the CT26 cells." (PMID 31799196, 2019). "Normal human MaSCs are defined as having CD49fpos/Epcamneg FACS profiles, indicating that the majority of Wnt1-EarlyEx tumor cells share similar features with normal MaSCs." (PMID 31213486, 2019). "Tumors that arose from the individual Wnt1-LateEx FACS populations were then re-analyzed with FACS to investigate their tumor profiles." (PMID 31213486, 2019). "Wnt1-LateEx tumors, however, continued to progress with erlotinib treatment with a median tumor growth of 109%." (PMID 31213486, 2019). "We found that TREM2 overexpression suppressed tumor growth in vitro and in vivo via the negative regulation of the Wnt1/β-catenin signaling pathway." (PMID 31489935, 2019). "Since elevated Myc also concomitantly suppresses expression of Wnt1, a key autocrine survival factor for mammary epithelial cells, tumors comprising only Mychigh tumor cells effectively starve themselves of autocrine survival signals." (PMID 31611367, 2019). "Tumor tissue lysates of CT26 cells that received exosomes from the CT26Flag−CAGE1 cells displayed higher expressions of Wnt1, β-catenin, cycinD1, pGSK3βSer9, and autophagic flux than tumor tissue lysates from the CT26 cells that received CT26 exosomes." (PMID 31799196, 2019). "We conclude that Wnt1-induced signaling rather occurs in the tumor microenvironment than in lymph nodes." (PMID 30926812, 2019). "Since MMTV-Wnt1–driven tumors are dependent upon Wnt signaling for their maintenance, Myc-induced down-regulation of Wnt1 effectively deprives the tumor cells of their own survival signal." (PMID 31611367, 2019). "As predicted, Wnt1-EarlyEx tumors had a dynamic reduction in tumor volume after only 14 days of treatment." (PMID 31213486, 2019). "Therapeutically, Wnt1-EarlyEx tumors showed a dynamic reduction in tumor volume when treated with an EGFR inhibitor." (PMID 31213486, 2019).
tumor (continued). "We present evidence that the CAGE-miR-140-5p-Wnt1 axis regulated cellular interactions within the tumor microenvironment mediated by exosomes." (PMID 31799196, 2019). "Disruption of C3aR expression dampened tumour growth and the expression of Wnt‐1, β‐catenin and Sox‐2 in the xenograft model." (PMID 30825266, 2019). "Accordingly, Wnt1-cDC-primed OTI T cells were less therapeutic upon transfer in OVA-LLC tumor-bearing hosts." (PMID 30926812, 2019). "Canertinib however, completely abrogated both TUBO and Wnt1 tumour cell migration in terms of both distance and number of cells after 10 days of treatment showing it to be the most effective therapy for these tumours." (PMID 30139956, 2018). "Similar to its effect on Wnt1 tumours, Canertinib showed a pronounced anti-migratory affect in TUBO tumours with no migratory colonies visible in 100% of samples regardless of adipocyte status." (PMID 30139956, 2018). "When they targeted Wnt1 clones to promote tumor regression, the basal cells restored tumor growth by recruiting heterologous Wnt-expressing cells." (PMID 29928478, 2018). "We previously demonstrated that the IGF-1R acts as a tumor and metastasis suppressor in the Wnt1 mouse model of TNBC." (PMID 30458886, 2018). "While examining the specific effects of three different inhibitors on Wnt1 tumour fragments we observed a striking increase in Wnt1 tumour cell migration during ROCKi treatment." (PMID 30139956, 2018). "Compared to other tumor models, Wnt1 tumors showed a significant increase in metabolites feeding into the one-carbon metabolism, dipeptide levels, and de novo synthesized amino acids, indicating more active protein metabolism." (PMID 29619217, 2018). "This is suggestive of a possible pro-survival/proliferative effect of ROCKi on migratory cells in Wnt1 tumours." (PMID 30139956, 2018). "In support, the immunohistochemical analysis of the tumor samples showed a higher expression level of NF-κB, Notch1 and WNT1 in DLD-1R tumors than its DLD-1 parental samples; a reverse observation was made in E-cadherin expression." (PMID 30005681, 2018). "Levels of betaine (and isobars containing betaine-aldehyde and N-methyldiethanolamine), an amino acid synthesized de novo from choline, is also higher in the Wnt1 tumors than in the other tumor groups." (PMID 29619217, 2018). "The first tumour model analysed was the well-established MMTV-Wnt1 transgenic mouse model where overexpression of the Wnt1 proto-oncogene is driven by the MMTV promoter, resulting in adenocarcinoma development in FVB mice." (PMID 30139956, 2018). "In the present study β-catenin band wnt1 staining was observed in the cytoplasm and/or nuclei of tumor cells as well as in oval cells within HCCs, indicating activation of Wnt1 signaling in human NASH-associated and STAM mice hepatocarcinogenesis." (PMID 28218651, 2017). "In tumor tissues enhanced expression of Arhu, a member of the Rho family that mediates in part the effects of Wnt1 signaling in the regulation of cell morphology, cytoskeleton organization and cell proliferation was observed." (PMID 29254206, 2017). "Inhibition of SOX2 expression in lung adenocarcinoma induces apoptosis of tumor cells and down-regulates WNT1/2, Notch1, and c-myc gene expression." (PMID 28870231, 2017). "We also confirmed that miR-149-3p played a tumor suppressor role by downregulating its direct target gene Wnt-1." (PMID 27713126, 2016).
tumor (continued). "We conclude that the frequently downregulated miR-148b can regulate WNT1/β-catenin signalling pathway and function as a tumor suppressor in HCC." (PMID 25627001, 2015). "Taken together, these data demonstrate that miR-148b can regulate WNT1 expression and function as a tumor suppressor in HCC development." (PMID 25627001, 2015). "WNT1 signaling and tumor growth are enhanced by syndecan-1 in mammary gland tumors, and syndecan-1 has a role in the ability of Wnt1 to induce the accumulation of mammary progenitor cells." (PMID 26420915, 2015). "Taken together, these results confirmed that the transplanted tumor model exhibited a similar histological pattern to the spontaneous Wnt1/iR1 tumors." (PMID 26581390, 2015). "We confirmed that Wnt1-positive populations mostly overlapped with LEF1-positive subpopulations in tumor xenografts." (PMID 26202299, 2015). "Using Wnt-1 tumour-bearing mice, they showed the presence of increased collagen in areas of hyperplasia before the development of palpable tumours." (PMID 26040322, 2015). "Since the Wnt1/iR1 tumor cells express an epitope HA tagged iFGFR transgene, immunofluorescence staining for K8, K5 and the HA tag also were performed to verify if the tumors were derived from the original transplants." (PMID 26581390, 2015). "In a further seven cases (7/9, 77.8%) the expression levels of Wnt1 were preserved from the primary tumor to the metastatic lesions." (PMID 25574191, 2015). "The recurrent tumors exclusively co-expressed K8 with the HA tag, indicating that these tumor cells were derived from the original transplanted Wnt1/iR1 tumor." (PMID 26581390, 2015). "Wnt1 was detected in cells of the tumor stroma and its presence tended to decrease, as the level of gastrin in the tumor increased." (PMID 24901518, 2014). "We have recently reported that M2-macrophages synthesize and secrete Wnt ligands which can modulate co-cultured epithelial cell behavior and in the present study we observed immunoreactivity for Wnt1 in cells of the tumor stroma." (PMID 24901518, 2014). "Analysis of non-tumor tissue demonstrated that expression of Wnt5a attenuated some of the effects of Wnt1 on the mammary gland including increased side branching and increased progenitor and basal cell populations." (PMID 25401739, 2014). "In all, 4/16 of the neoplasia expressed Fgf3, 7/16 expressed Wnt-1, 6/16 expressed Wnt10b, and 11/16 expressed Rspo2." (PMID 23866257, 2013). "Several of these mouse-specific classes, however, had clear basal-like tumor expression features, including WapINT3Ex, Wnt1-LateEx, Wnt1-EarlyEx, and Squamous-likeEx." (PMID 24220145, 2013). "To elucidate the relationship of SLD5 to cancer cell growth in tumor progression in vivo, we investigated oncogenesis in the Wnt1/C2mE transgenic mouse, a genetic model of spontaneous gastric carcinogenesis, on an SLD5+/− background (SLD5+/−/Wnt1/C2mE)." (PMID 24244394, 2013). "While caErbB2 induced tumors much more rapidly than Wnt1, each parous group developed tumors significantly faster than its corresponding virgin control cohort and with higher tumor multiplicity." (PMID 24381245, 2013).
tumor (continued). "MMTV integration near the Wnt1/Wnt10b and Fgf3/Fgf4 loci can lead to the expression in the same tumor of one or the other or both genes in these clusters." (PMID 23131872, 2012). "Int-1 (Wnt1) was the first gene discovered to be activated by an integrated provirus in the MMTV tumor models." (PMID 22303459, 2012). "The Fzd8 soluble extracellular domain suppresses Wnt-driven tumor growth in vivo and two sFRPs, FrzA and FrzB inhibited Wnt-1–mediated increase in cytoplasmic β-catenin levels, TCF transcriptional activity in vitro, and tumor growth and metastasis." (PMID 22606268, 2012). "Intratumoral injection of anti-Wnt-1 antibody also suppresses tumor growth in a Huh7 xenograft model via induction of tumor cell apoptosis." (PMID 21188169, 2011). "We have previously shown that Lrp5 is necessary for tumor development in response to Wnt1, despite the co-expression of functional Lrp6 in basal mammary epithelial cells." (PMID 21541292, 2011). "The Wnt1-induced mouse mammary model is significant to our understanding of tumor stem cells, for at least two reasons." (PMID 21541292, 2011). "Wnt signaling (via Lrp5 and Wnt1) is therefore necessary and sufficient for cell growth and tumor maintenance." (PMID 21541292, 2011). "If Lrp5 expression is required to close a paracrine Wnt1-signaling loop that determines cell survival and tumor initiating activity, then Lrp5-positive cells should include most of the tumor stem cells." (PMID 21541292, 2011). "We examined the micro-vessel density in Wnt1 and Her2 tumors by immunohistochemical staining of tumor sections with anti-CD31 antibody, a platelet endothelial cell adhesion molecule (PECAM1) marker." (PMID 20087418, 2010). "Following antibody treatments, average Wnt1 tumor size in the anti-Gr1 group was inhibited by 53% relative to control anti-GD treated group (p = 0.034), which was similar to the levels of inhibition by anti-SDF1." (PMID 20087418, 2010). "Early onset tumor formation in MMTV/Wnt1 mice is significantly delayed by expression of a dominant-interfering PEA3 mutant, and expression of this dominant negative PEA3 transgene is markedly reduced in tumors relative to non-tumorous mammary tissues." (PMID 20107508, 2010). "The involvement of Gr1+ cells was evident from the retardation of Wnt1 tumor growth following in vivo depletion of these cells with an anti-Gr1-specific antibody." (PMID 20087418, 2010). "The impact of anti-SDF1 treatment on Wnt1 tumor growth prompted us to examine the mechanism by which SDF1 contributes to Wnt1 tumor growth." (PMID 20087418, 2010). "Recent studies have shown that Wnt1 tumors recruit BMDCs to the tumor site, and these progenitor cells can be incorporated into the stroma, possibly contributing to tumor angiogenesis." (PMID 20087418, 2010). "Following treatments, anti-SDF1 antibody significantly inhibited Wnt1 tumor growth, and the average tumor size of control anti-GD treated group (n = 10) was 1,266 mm3 where as anti-SDF1 treated group was 674 mm3 (p = 0.029)." (PMID 20087418, 2010).
tumor (continued). "Consistent with the FACS data, Wnt1 tumor sections stained with anti-MECA32 antibody contained a higher proportion of MECA32+ cells than in Her2 tumor sections." (PMID 20087418, 2010). "Specifically, the dominant-interfering mutant ΔNPEA3En suppressed early onset tumor formation in MMTV/Wnt1 mice, and ΔNPEA3En expression was markedly suppressed in those tumors that did develop in bigenic MMTV/Wnt1, MMTV/ΔNPEA3En animals." (PMID 20107508, 2010). "Because these experiments were done in mice with germ line KO of RARα1, to link the effect to the tumor itself, we transplanted fragments of wnt1-RARα1/KO and wnt-tumor on the contralateral sides of four wt-mice between the third and the fourth mammary gland." (PMID 20923554, 2010). "Isolation of various cell types from Wnt1 tumors revealed that SDF1 was produced by both tumor myoepithelial cells and stromal cells, whereas Her2 tumors lacked myoepithelial cells and contained significantly less stroma." (PMID 20087418, 2010). "Wnt1 and Her2 tumor-bearing mice were injected with anti-Gr1 (twice per week), anti-SDF1 (three times per week), and a combination of both antibodies." (PMID 20087418, 2010). "The median time to tumor formation was 145 days in MMTV/Wnt1 mice compared to 192 days in those animals also bearing the ΔNPEA3En transgene." (PMID 20107508, 2010). "In summary, we showed that loss of RARα1 leads to reduced mammary stem cell content and an increase in wnt1-tumor free survival in mice." (PMID 20923554, 2010). "Previously, we showed that Lrp5 null mammary glands, though grossly normal (albeit developmentally delayed), were remarkably resistant to Wnt1-induced tumor development." (PMID 19672307, 2009). "Because Wnt proteins are indispensible for cancer cell growth and survival, we studied the potential anti-tumor effect of anti-Wnt-1 antibody in HCC cells." (PMID 19778454, 2009). "Because of the functional importance of Wnt-1 in HCC development and progression, we investigated the anti-tumor effects of blocking Wnt-1 mediated signaling through the Wnt/β-catenin pathway in human HCC." (PMID 19778454, 2009). "The median time to tumor formation (MTTF) was 31 weeks (n = 31) for female SAFB1+/+/Wnt-1, and 34 weeks for female SAFB1+/-/Wnt-1 mice (n = 29)." (PMID 19267898, 2009). "We next studied the in vivo effects of the anti-Wnt-1 antibody on tumor growth in a HCC xenograft model in nude mice." (PMID 19778454, 2009). "Hh pathway activity also occurred within tumor-associated stromal and K14+/p63+ subpopulations in a manner correlated with Wnt1 tumor onset." (PMID 19225568, 2009). "When immunostained with anti-c-Myc, cyclin D1, and survivin antibodies, tumor tissues that had been treated with anti-Wnt-1 antibody showed reduced c-Myc, cyclin D1, and survivin expressions." (PMID 19778454, 2009). "Compared with PBS control, the anti-Wnt-1 antibody effectively inhibited tumor growth in vivo (ANOVA, P < 0.05, compared with PBS control at the beginning of the third week)." (PMID 19778454, 2009). "Expression of Wnt-1 in HCC tissues was at least 1.5 fold greater than in paired non-tumor tissues in four out of the seven tissue pairs." (PMID 19778454, 2009). "The effect of Rapamycin on primary Wnt-1 tumor cell proliferation was determined in vitro on cells obtained from individual mouse tumors." (PMID 18570671, 2008). "Given this information, we examined the effect of Rapamycin-resistant CD8+ and CD4+ T-cells on Wnt-1 tumor growth in vivo." (PMID 18570671, 2008). "Consistent with suppression of the mTOR pathway, decreased 4E-BP1, p70 S6-kinase, and S6 protein phosphorylation correlated with a decrease in Wnt-1 tumor cell proliferation." (PMID 18570671, 2008). "To evaluate the cellular mechanisms operational during Rapamycin induced inhibition of Wnt-1 growth we obtained purified primary tumor cells in vitro." (PMID 18570671, 2008).